INS (insulin)
Diseases named in the same sentence as INS in open-access papers (continued):
Sharing a sentence is not in itself a finding about the gene and the disease.
Hyperglycemia (continued). "Hyperglycemia, i.e., elevated blood glucose, is common in preterm babies, due to the immaturity of glucose regulation mechanisms; it is often treated with insulin infusion, based on weak evidence." (PMID 33306685, 2020). "In HHS there is enough insulin activity to prevent ketosis, but insufficient insulin activity to prevent hyperglycaemia." (PMID 32704574, 2020). "On the contrary, depletion of the diabetic gut microbiota by antibiotics treatment in diabetic mice significantly enhanced the therapeutic effects of ADSCs as measured by reversal of hyperglycemia, insulitis, and increased insulin output." (PMID 32483466, 2020). "Decreased insulin sensitivity in the liver leads to elevated liver glucose production, hyperinsulinemia, increased beta-cell mass, and hyperglycemia." (PMID 32714403, 2020). "After its digestion, a rapid increase in amino acids (BCAAs, in particular) results in increased insulin release which probably improves postprandial hyperglycemia." (PMID 32958070, 2020). "It is characterized by hyperglycemia which is due to either paucity of insulin secretion by pancreatic β-cells or inefficiency of cells to use insulin against glucose." (PMID 32707893, 2020). "In women experiencing hyperglycemia only in the morning fasting state, intermediate insulin, such as NPH, or detemir should be administered at bedtime, as a single dose." (PMID 33371325, 2020). "The results of impaired insulin effect are hyperglycemia and imbalance of metabolism, which lead to hyperlipidemia, inflammation and consequently oxidative stress." (PMID 32824505, 2020). "DM, a chronic metabolic and degenerative disease is characterized by hyperglycemia due to defective insulin secretion or insulin dysfunction." (PMID 33204324, 2020). "Glyburide (5-chloro-N(2-{4-[N-(N-cyclohexylcarbomoyl)sulfamoyl]phenyl}ethyl)-2-methoxybenzamide) belongs to the sulphonylurea class of antidiabetic agents, which stimulates insulin secretion from pancreatic beta cells, thereby reducing hyperglycaemia." (PMID 32442232, 2020). "T2D is characterized by hyperglycemia, pancreatic β-cell dysfunction, decreased insulin signaling action, and increased hepatic glucose formation." (PMID 32999320, 2020). "It is possible that this relates to the fact that these neonates have plentiful glucose stores, but develop hypoglycemia because of high insulin secretion induced by maternal and fetal hyperglycemia." (PMID 32609748, 2020). "In contrast, not using early-PN lowered blood glucose and plasma insulin concentrations in the current study, in line with the earlier finding of a lowered insulin requirement to prevent hyperglycemia." (PMID 32867803, 2020). "In T2D, hyperglycemia is the consequence of insufficiency of insulin secretion from the pancreatic β cells and inability of target organs to respond to insulin." (PMID 33043040, 2020). "DM is a collection of metabolic disorder characterized by hyperglycemia owing to insulin production defects and/or insulin action." (PMID 33255958, 2020). "The extent and degree of hyperglycemia events and insulin resistance during infection incidence directly correlate with the type of pathogen, the type of hormone involved and the severity of the infection." (PMID 32784178, 2020). "A series of in vitro tests were carried out in GIT-mimicking conditions, before investigating the effect of orally administered insulin-loaded particles on hyperglycemia in diabetic Wister–Kyoto rats (WKY)." (PMID 32751231, 2020). "A similar broad range of insulin doses was observed for patients with severe hyperglycaemia, glucose ranging from 300 to 325 mg/dL." (PMID 32612144, 2020). "Eight patients were excluded after enrollment, 4 because of renal failure, 1 because of recurrent hypoglycemia while taking metformin alone, 1 because of hyperglycemia requiring insulin therapy, and 2 because of terminal illness." (PMID 33361237, 2020).
Hyperglycemia (continued). "Upon removal of insulin implants after 1 month, a recurrence of hyperglycemia was observed, and Kuma mutant mice still showed impaired glucose tolerance, which was not significantly different from those of the untreated group." (PMID 32699230, 2020). "The low insulin level in type I diabetes is due to autoimmunity in beta cells of the pancreas, and the resulting hyperglycemia can be managed by administering insulin injections subcutaneously." (PMID 32848717, 2020). "Although hyperglycemia can be ameliorated by drugs or exogenous insulin administration, these treatments cannot provide physiological regulation of blood glucose." (PMID 32641151, 2020). "There is an unmet need to effectively manage hyperglycemia in conjunction with the use of insulin in T1D patients." (PMID 31935938, 2020). "That molecule facilitates glucose uptake by skeletal muscles, improves hepatic glucose and lipid metabolism, influencing a positive effect on hyperglycemia and hyperlipidemia and thereby acting as an insulin sensitizing hormone." (PMID 32917052, 2020). "Further studies are warranted to dissect the role of hyperglycemia versus saturated fatty acid and altered insulin signaling in diabetic versus obese pre-diabetic or insulin-resistant conditions." (PMID 32492941, 2020). "Glucotoxicity, the toxic effects of persistent and progressive hyperglycaemia, further impairs insulin secretion in T2DM patients." (PMID 32566685, 2020). "In particular, the metabolic defects in the SMA Smn 2B/− mice model were characterized by fasting hyperglycemia, glucose intolerance, hypersensitivity to insulin, and hyperglucagonemia." (PMID 33339220, 2020). "In support of this possibility, it has been reported that the treatment of diabetic mice with insulin corrected the hyperglycemia along with a rapid and complete return of serum GPLD1 activity and liver mRNA." (PMID 32467736, 2020). "In patients that require insulin, the dose and timing of administration depend on the patient’s body weight, gestational age, and the time of day at which hyperglycemia is occurring." (PMID 33371325, 2020). "The toxic effects of hyperglycemia and some lipid fractions also favor an increase in the resistance of insulin-dependent tissues to the action of insulin, thus enhancing IR and its metabolic consequences." (PMID 33233346, 2020). "Overall, these studies demonstrate that this new class of copolymer biomaterials seeded with islets can support cell viability and glucose-responsive insulin production to restrain hyperglycemia in diabetic recipients." (PMID 32152396, 2020). "Currently, all diagnostic tests for T2D are based either on the determination of glycemia, insulin or its secreted precursor C-peptide levels or on the assessment of the consequences of hyperglycemia, e.g., hemoglobin glycation (HbA1c levels)." (PMID 33665204, 2020). "It is expected that in our animal model of high-sucrose feeding circulating levels of both insulin and c-peptide would be upregulated, as a pancreatic compensatory mechanism to prevent hyperglycemia and maintain glucose homeostasis." (PMID 32942712, 2020). "We proposed that hyperglycaemia can induce podocyte apoptosis by inhibiting the action of podocyte survival factors, thus inactivating the cellular effects of insulin signalling." (PMID 32238837, 2020). "Plasma insulin levels are variably reported as raised or depressed in sepsis, but insulin resistance is commonplace regardless, with subsequent hyperglycemia‐inducing toxicity." (PMID 32176432, 2020). "It has been reported that metformin or AICAR attenuates Ang II-induced atheromatous plaque formation and protects against hyperglycemia-induced atherosclerosis and also reduces insulin resistance." (PMID 33511118, 2020). "Using the herein developed methods, we show that, in a mouse model of S961-induced hyperglycemia and impaired insulin sensitivity, there is an overall increase in beta cell volume and islet number." (PMID 33158929, 2020).
Hyperglycemia (continued). "This was achieved in most of the studies by injecting a toxin to insulin producing cells of the pancreas, such as streptozotocin, and also a citrate compound, to quickly induce hyperglycaemia in tissue." (PMID 32876648, 2020). "Type 1 diabetes is characterized by hyperglycemia due to the cellular-mediated autoimmune destruction of pancreatic β cells which leads to the production of less insulin." (PMID 32410865, 2020). "These insulin analogs are primarily suitable for patients with postprandial hyperglycemia, which can be injected 0–15 min before or immediately after meal, and always with great compliance." (PMID 32850735, 2020). "The disease is characterized by the destruction of beta cells, leading to hyperglycemia, and to a lifelong insulin-dependent state." (PMID 32670194, 2020). "During hyperglycemia, pancreatic β-cells are exposed to higher glucose concentrations which amplifies the glucose enhanced signal of insulin secretion through exocytosis of insulin granules in a time-dependent manner." (PMID 32877990, 2020). "Her symptoms, hyperglycemia, and ketoacidosis were alleviated by rapid normal saline infusion and insulin administration." (PMID 32967631, 2020). "Patients were assessed twice during fasting month for insulin dose adjustment and documentation for any hyperglycemia or hypoglycemia." (PMID 33425548, 2020). "Among the three formulations, insulin aspart-loaded BaSO4 and BaCO3 particles dramatically reduced the existing hyperglycemia." (PMID 32751231, 2020). "The α-glucosidase inhibitors were effective in almost all patients with high postprandial hyperglycemia as monotherapy or in combination with other oral hypoglycemic agents or insulin." (PMID 32256656, 2020). "Pain was also associated with: injecting through clothes, injecting cold insulin, LH, injecting into LH, incorrect site rotation, hypoglycemia and hyperglycemia, higher HbA1c levels, lower BMI, younger age, and higher doses of insulin." (PMID 32071879, 2020). "In the condition of fasting insulin resistence, after glucose loading, the presence of marked hyperglycemia during ipGTT can be interpreted as a further worsening of resistance and/or reduced production of insulin." (PMID 32117058, 2020). "In fact, insulin not only prevents the deleterious effects of hyperglycemia by improving the anabolism of glucose, proteins, and lipids but also promotes a systemic anti-inflammatory response through the reduction of proinflammatory cytokines." (PMID 32626786, 2020). "Previous work has shown hyperglycemia and elevated circulating insulin levels in Bbs4-/- mice at 4–6 months of age." (PMID 33200981, 2020). "This so-called “stress hyperglycemia” results from the release of counter-regulatory hormones (glucagon, cortisol, and epinephrine), which oppose the action of insulin." (PMID 33297385, 2020). "There are few studies which specifically focus on treatment of GC induced hyperglycemia, and most prospective studies investigate glucose control with different insulin regimens." (PMID 33348743, 2020). "Stress hyperglycemia, which is a reflection of high free fatty acids, insulin resistance, and steroid hormones, affects the course of the disease in an adverse way." (PMID 32819275, 2020). "Despite the poorly controlled hyperglycemia, less than half of patients in our study had initiated insulin treatment compared with results from the former study which was carried out in T2DM outpatients." (PMID 32267843, 2020). "In vivo, treatment of HF/HFr-fed mice with MS-275 ameliorated hyperglycemia, insulin resistance, stress signals, and TNF-α expression in skeletal muscle." (PMID 33362555, 2020). "As beta-cell mass and function decrease, circulating insulin levels decrease and hyperglycemia ensues." (PMID 32582035, 2020). "Insulin use and increased HbA1c level often indicate poor glucose control and hyperglycemia downregulates LRP1 expression in the brain." (PMID 33013281, 2020).
Hyperglycemia (continued). "Management of HNF1B-MODY involves treatment of renal disease and early intensive insulin therapy to control hyperglycemia and delay the onset of microvascular complications." (PMID 33292863, 2020). "Glucocorticoid (GC)-induced hyperglycemia is characterized by elevated postprandial blood glucose, which commonly requires multiple insulin injections." (PMID 32381085, 2020). "Another study supported this findings by showing increased levels in insulin resistant humans, which positively correlated with hyperglycemia." (PMID 33178196, 2020). "While insulin promotes cells absorbing glucose, thus reducing blood glucose levels to prevent hyperglycemia, glucagon signals for the release of stored glucose from the liver, resulting in increased blood glucose levels to prevent hypoglycemia." (PMID 32993686, 2020). "Rapid infusion of normal saline and insulin administration alleviated hyperglycemia and ketoacidosis." (PMID 32967631, 2020). "High CHO levels in the diet result in hyperglycemia in rainbow trout, which activates the components of the insulin-signaling cascade." (PMID 33142948, 2020). "In beta cells, the impaired mitochondrial energy metabolism is accompanied by reduced insulin secretion at all glucose levels, but the differences, compared to a normal beta cell, are the most pronounced in hyperglycemia." (PMID 33327428, 2020). "This “glucose toxicity” contributes to the progressive worsening of hyperglycemia, and as the disease progresses, most patients with T2D require higher doses of insulin to maintain glycemic control." (PMID 32351447, 2020). "Glycine is known to be sweet and improves insulin sensitivity along with a reduction of symptoms induced by hyperglycemia, albeit at higher concentrations than what we coated our nanoparticles." (PMID 32120819, 2020). "In this study, we demonstrated a decrease in adiponectin levels after correction of hyperglycemia with insulin treatment." (PMID 31905496, 2020). "Abnormalities in the mechanism of insulin secretion will reduce glucose intake by cells while rising blood sugar levels will result in a state of hyperglycemia." (PMID 33281368, 2020). "Glycemia and urine volume were similar (p > 0.05) in ND and D+I animals, indicating that insulin treatment completely reverted hyperglycemia and higher urine volume described in D rats." (PMID 32182246, 2020). "The risk of hyperglycemia in diabetic nephropathy has been well documented; it is now necessary to focus more on high FFA levels, also caused by insufficient insulin action, as a risk factor for diabetic nephropathy." (PMID 33150239, 2020). "For hyperglycaemia, anti-diabetic treatment influenced only the event frequency, with an eight-fold incidence rate of ED attendances for insulin users." (PMID 32429960, 2020). "Animal and human-based studies have shown that lycopene reduces blood pressure, atherosclerotic burden and improves blood antioxidant capacity, has an anti-obesity role, improves insulin sensitivity, reduces hyperglycemia, and improves the lipid profile." (PMID 32933003, 2020). "TDD of insulin, and bolus/basal ratio in our findings also indicate that more therapeutic emphasis be put on postprandial hyperglycemia." (PMID 32267843, 2020). "To determine the mechanism whereby SP ameliorates hyperglycemia, we measured the expression and phosphorylation of insulin-signaling intermediates and GLUT4." (PMID 32041272, 2020). "Pharmacological blockade of CB1Rs significantly reduces hyperglycemia, improves glucose tolerance and/or insulin sensitivity in obese diabetic Zucker rats or diet-induced obese mice and humans." (PMID 33093533, 2020). "In these instances, it is crucial for physicians to determine the reasons of uncontrolled hyperglycaemia, to discuss with patients about the benefits of insulin therapy and the consequences of uncontrolled hyperglycaemia." (PMID 32318640, 2020).
Hyperglycemia (continued). "Together with impaired insulin secretion and sensitivity, higher levels of hepatic gluconeogenesis result in the hyperglycemia observed in GDM patients." (PMID 32252821, 2020). "The flux of glucose from liver to muscle during exercise is impacted by insulin treatment, which can result in either hypo- or hyperglycaemia." (PMID 32533229, 2020). "The liver responds to the insulin stimulation by terminating the release of glucose into the bloodstream, whereas sustained hyperglycemia is one of the factors that impairs the biological actions of insulin." (PMID 33302435, 2020). "The algorithm utilized CGM data, carbohydrate data and insulin data and trained an extreme gradient-based tree algorithm to predict three conditions 6 h after meal consumption: hyperglycemia, in target range, and hypoglycemia." (PMID 32517068, 2020). "Goto-Kakizaki (GK) rats were established by repeated inbreeding of glucose intolerant rats and display hyperglycemia as a result of diminished insulin release from β-cells." (PMID 32394191, 2020). "During feeding, pancreatic β-cells secrete insulin in response to elevated levels of nutrients, especially glucose (postprandial hyperglycemia) and simultaneously activate insulin biosynthesis for future secretions." (PMID 36844373, 2020). "For example, hyperglycemia was the key initial factor of DN, while renal hemodynamic changes and insulin resistance also played a key role in the formation of DN." (PMID 32266256, 2020). "The increased fasting glucose, HbA1c, and insulin levels (all p < 0.001) in db/db mice indicate a successful induction of hyperglycemia and hyperinsulinemia in the ObD model." (PMID 32842462, 2020). "A pro-inflammatory state contributes, along with hyperglycemia and decreased insulin signaling, to a deregulated metabolism and excessive generation of ROS." (PMID 32825356, 2020). "While both groups develop hyperinsulinemia, diabetic‐obese individuals become insulin resistant, leading to β‐cell dysfunction, hypoinsulinemia, and hyperglycemia." (PMID 33113267, 2020). "Chorea in the context of hyperglycemia is a reversible and infrequent occurrence, best managed with insulin and haloperidol combination therapy." (PMID 32642387, 2020). "Previous in vivo studies demonstrated that free systemically administered tesa can reduce hypertriglyceridemia, hyperinsulinemia, and hyperglycemia in ob/ob mice and restore insulin sensitivity in obese Zucker rats." (PMID 31918918, 2020). "Hyperglycaemia induced by chronic intravenous injection of elastin-derived peptides was mitigated by DANA through the improvement of insulin sensitivity." (PMID 32251344, 2020). "The gluco-centric paradigm views hyperglycemia as the primary target, being driven by resistance to insulin combined with progressive beta cells failure, and considers glycemic control its ultimate treatment goal." (PMID 32128655, 2020). "Gestational diabetes mellitus (GDM) develops when insulin secretion from pancreatic beta cells is insufficient to respond to the increased insulin requirements of pregnancy, resulting in hyperglycemia of variable severity." (PMID 31921323, 2020). "It has been defined as gestational diabetes mellitus is characterized by hyperglycemia or glucose intolerance with onset during pregnancy resulting from defects in insulin secretion or insulin action." (PMID 33110438, 2020). "The recorded results showed that hyperglycemia was the most remarkable metabolic disorder of sodium pentobarbital higher doses which was attributed to induction of hepatic insulin resistance." (PMID 31942001, 2020). "In type 1 diabetes (T1D), an autoimmune disease, insulin-producing pancreatic β-cells are destroyed, resulting in hyperglycaemia due to insulin insufficiency." (PMID 32321922, 2020). "Despite hyperglycemia, we were unable to detect significant changes in fasting insulin levels throughout the study." (PMID 32601405, 2020).